SNORA9 (small nucleolar RNA, H/ACA box 9)
Synonyms: ACA9; SNORA9A
Gene: Small nucleolar RNA gene on chromosome 7 (44,985,378 to 44,985,510, reverse strand). Ensembl gene ENSG00000277184.
Gene Ontology:
Biological process: RNA processing
Cellular component: nucleolus
Homologues: Orthologues: pig SNORA9 (91% identical). Paralogues in human: SNORA9B (92% identical).